CRYAB (crystallin alpha B)
Diseases named in the same sentence as CRYAB in open-access papers (continued):
Sharing a sentence is not in itself a finding about the gene and the disease.
diabetes (5 papers, 2013 to 2022). "Among these proteins, one of particular interest is α-basic crystalline (CRYAB), an ER stress-inducible chaperone, which shows over 40% of decrease in diabetes." (PMID 28522876, 2017).
gastric cancer (5 papers, 2021 to 2025). A primary or metastatic malignant neoplasm involving the stomach. "CRYAB is a small heat shock protein that can promote the migration and invasion of gastric cancer cells by mediating EMT through NF-κB signaling." (PMID 39895782, 2025).
glaucoma (5 papers, 2014 to 2022). Increased pressure in the eyeball due to obstruction of the outflow of aqueous humor. "Moreover, the expression levels of many other marker proteins such as GFAP, heat shock protein 27 (Gene name: HSP27), or α-crystallin B chain (Gene name: CRYAB) have been correlated with an elevated intraocular pressure (IOP), one of the main risk factors of glaucoma development." (PMID 31470587, 2019).
bladder cancer (4 papers, 2020 to 2022). "CryAB inhibits migration and invasion of the cancer cells in bladder cancer cells by decreasing PI3K and AKT signaling, suggesting that CryAB acts as a tumor suppressor." (PMID 34831344, 2021). "Decreased expression of CRYAB indicated its tumor suppressor function in bladder cancer." (PMID 33245713, 2020).
dilated cardiomyopathy (4 papers, 2008 to 2025). Cardiomyopathy which is characterized by dilation and contractile dysfunction of the left and right ventricles. "Taken together, these comparative data strengthen our conclusion that the CRYAB p.Arg123Gln variant contributes to both dilated cardiomyopathy and long QT syndrome, supporting a dual structural–electrical role of CRYAB in cardiac pathophysiology." (PMID 41153379, 2025). "In this study, we report a previously uncharacterized missense variant in the CRYAB gene (c.368G>A; p.Arg123Gln) identified in a large multigenerational family affected by both dilated cardiomyopathy (DCM) and long QT syndrome (LQTS)." (PMID 41153379, 2025). "In a similar manner, dominant negative forms of alphaB-crystallin (CryAB) result in cytoplasmic CryAB misfolding/aggregation and reductive stress in the mouse heart, ultimately leading to dilated cardiomyopathy." (PMID 25996830, 2015). "Interestingly, mutations in the human CRYAB gene cause disease phenotypes that are strikingly similar to those observed for lamin associated muscular dystrophy, including skeletal muscle weakness and dilated cardiomyopathy in cases of lamin-associated muscular dystrophy." (PMID 25996830, 2015).
head and neck carcinoma (4 papers, 2022 to 2023). A carcinoma that arises from the head and neck region. "Some of these genes are even associated with a characteristic role in the tumorigenesis of head and neck carcinoma (like SOX2, CRYAB, and PTHLH)." (PMID 37455825, 2023).
Huntington disease (4 papers, 2019 to 2021). Huntington disease (HD) is a rare neurodegenerative disorder of the central nervous system characterized by unwanted choreatic movements, behavioral and psychiatric disturbances and dementia. "Our previous study demonstrated that HSF2 deficiency accelerated disease progression and shortened lifespan in a mouse model of Huntington’s disease, suggesting that HSF2 could be a potential therapeutic target for neurodegenerative diseases by regulating the expression of αB-crystallin (CRYAB)." (PMID 35087869, 2021).
melanoma (4 papers, 2018 to 2023). A malignant, usually aggressive tumor composed of atypical, neoplastic melanocytes. "Further evaluation of TCGA cancer genomic data collection reveals loss of copy number for the αB-Crystallin encoding gene CRYAB in over 15% of melanoma cases." (PMID 36329064, 2022). "Although there is no direct nor mechanistic evidence of the MITF-CRYAB transcriptional axis in other cancer types, in melanoma both MITF and CRYAB expression are upregulated by BRAF/MEK-inhibitor treatments, suggesting that this regulation can go beyond both PCa scenario." (PMID 30310055, 2018).
myocardial infarction (4 papers, 2018 to 2025). Gross necrosis of the myocardium, as a result of interruption of the blood supply to the area, as in coronary thrombosis. "CRYAB was also identified as a downstream effector of calcineurin-induced protection against cardiomyocyte apoptosis and a molecular switch in bypassing mitochondrial pathway of apoptosis during myocardial infarction." (PMID 34041241, 2021).
nasopharyngeal carcinoma (4 papers, 2018 to 2022). A carcinoma arising from the nasopharyngeal epithelium. "CRYAB has been reported to be a potential therapeutic target for nasopharyngeal carcinoma." (PMID 34249761, 2021). "However, in PCa and nasopharyngeal cancers, CRYAB expression is decreased, pointing at possible tumor-suppressive activity of CRYAB in these cancer scenarios." (PMID 30310055, 2018).
cervical cancer (3 papers, 2016 to 2023). A primary or metastatic malignant neoplasm involving the cervix. "In terms of the obtained results, the hub proteins KAT2B, PARP1, CDK1, GSK3B, WNK1, and CRYAB have been associated with several cancers in previous studies, but their association with cervical cancer is proposed here for the first time." (PMID 30020984, 2018). "Although Gal-7 affects the specific cervical cancer networks in different ways, we identified a group of eight molecules that are regulated in both cell lines: CRYAB, TACSTD2, BCL-3, COX19, OASL, CDKN2A/p14ARF, NIBAN/FAM129A, and FST." (PMID 27558259, 2016). "However, the transcriptome datasets utilized here represented CRYAB as being down-regulated in cervical cancer." (PMID 30020984, 2018). "Furthermore, the KAT2B, PARP1, CDK1, GSK3B, WNK1, and CRYAB, proteins are associated with various cancer types, but their roles in cervical cancer have not been identified." (PMID 30020984, 2018).
hypertrophic cardiomyopathy (3 papers, 2017 to 2024). A condition in which the myocardium is hypertrophied without an obvious cause. "CRYAB modulates cardiomyocyte apoptosis in cardiac disorders, ANK2 regulates cardiac ion channels, and MYOZ2 mutations are linked to hypertrophic cardiomyopathy." (PMID 38559672, 2024). "Expression of CryAB has been reported to be greatly induced in the cardiac tissue of patients with familial hypertrophic cardiomyopathy, desmin-related cardiomyopathy, and pressure-overload cardiac hypertrophy." (PMID 29088822, 2017).
lupus (3 papers, 2022 to 2024). "Research findings indicate that the atypical expression of CRYAB has been implicated in various autoimmune disorders, including rheumatoid arthritis and systemic lupus erythematosus, as well as inflammatory conditions such as pneumonia and myocarditis." (PMID 38274814, 2023). "For instance, it has been reported that the small heat shock protein (sHsp), alpha-B crystallin (HSPB5; CRYAB), attenuates the severity and disease progression of LN in lupus-prone mice (positive chaperonopathy)." (PMID 38891798, 2024).
non-small cell lung carcinoma (3 papers, 2021 to 2023). A group of at least three distinct histological types of lung cancer, including non-small cell squamous cell carcinoma, adenocarcinoma, and large cell carcinoma. "Macrophages promote the metastasis of non-small cell lung cancer by upregulating CRYAB." (PMID 34354750, 2021).
anaplastic thyroid carcinoma (2 papers, 2015 to 2020). "TFCP2L1 is a crystallin, alpha B (CRYAB) gene promoter interacting transcription factor and lower expression of TFCP2L1 and CRYAB was revealed in anaplastic thyroid carcinomas compared to benign goiters." (PMID 25923053, 2015).
astrocytoma (2 papers, 2007 to 2014). "Major targets identified in our analysis, such as GFAP, CRYAB and TPIS, are major interactors of 14-3-3ζ and are powerful discriminators of low-grade astrocytoma." (PMID 25050814, 2014).
Cerebral ischemia (2 papers, 2016 to 2022). Restriction of arterial blood supply to the brain associated with insufficient oxygenation to support the metabolic requirements of the tissue. "In summary, our study demonstrates that Sino possesses potent therapeutic effects in cerebral ischemia and suppresses neuroinflammatory injury via targeting astrocytic DRD2 and the CRYAB/STAT3 pathway." (PMID 27724964, 2016).
distal myopathy (2 papers, 2018 to 2023). Distal myopathy refers to a group of muscle diseases which share the clinical pattern of predominant weakness and atrophy beginning in the feet and/or hands. "Heterozygous missense mutation p.(Gly154Ser) in the CRYAB gene, a variation that maps on the C-terminal region of the protein, has been associated with a late-onset progressive distal myopathy without cardiac involvement or isolated cardiomyopathy." (PMID 37511242, 2023).
endometriosis (2 papers, 2019 to 2024). The growth of functional endometrial tissue in anatomic sites outside the uterine body. "Indicative of a higher state of cellular stress, we also found that the decidualizing cells of donors with endometriosis displayed higher expression of stress response genes, such as CRYAB, HSD11B1 and GLRX." (PMID 38402336, 2024).
Epstein-Barr virus infection (2 papers, 2015 to 2024). An infection that is caused by Epstein-Barr virus. "Later it was shown that Epstein Barr virus infection induced CRYAB expression in B cells, and T cells reactive to CRYAB were identified both in healthy controls and patients with MS." (PMID 38433828, 2024).
ischemia (2 papers, 2018 to 2022). A hypoperfusion of the BLOOD through an organ or tissue caused by a PATHOLOGIC CONSTRICTION or obstruction of its BLOOD VESSELS, or an absence of BLOOD CIRCULATION. "CRYAB is believed to be a critical anti-apoptosis protein that regulates cardiomyocyte apoptosis induced by ischemia." (PMID 29867551, 2018).
ischemic stroke (2 papers, 2016 to 2021). A stroke disorder caused by obstruction of blood flow to the brain, due to thrombotic (local blood clot formation) or embolic (due to a blood clot or other material traveling from another site) event. "As expected, CryABR120G protein was also identified from the protein aggregates of CryABR120G mouse heart, whereas protein aggregates isolated from the Ntg mouse brains following ischemic stroke only contained wild-type CryAB." (PMID 33472658, 2021). "Our study demonstrates that Sino activates astrocytic DRD2 and thereby suppresses neuroinflammation via the CRYAB/STAT3 pathway, which sheds some light on a promising therapeutic strategy for ischemic stroke." (PMID 27724964, 2016). "Our results indicated that Sino suppresses the neuroinflammation via targeting the astrocytic DRD2/CRYAB/STAT3 pathway in cerebral ischemic model in vivo and in vitro, which sheds some light on a promising therapeutic strategy for ischemic stroke." (PMID 27724964, 2016).
kidney cancer (2 papers, 2021 to 2023). Primary or metastatic malignant neoplasm involving the kidney. "In particular, ELF5, SLC17A3, RALBP1, WNK1, APOC1, and CRYAB were experimentally verified to play an important role in the occurrence and development of kidney cancer." (PMID 34445498, 2021).
long QT syndrome (2 papers, 2012 to 2025). "Indeed, the majority of dystrophinopathy patients have arrhythmias, long QT syndrome and contractile dysfunction, and therefore overlap in phenotype with patients with mutations in cypher, CRYAB, Ahnak1, or Cavin-1." (PMID 22937058, 2012).
Lymph node metastasis (2 papers, 2019 to 2020). "Univariate analysis showed that DFS prognosis was associated with CRYAB expression, histological type, Lymph node metastasis, distant metastasis, and tumor TNM stage." (PMID 31152111, 2019). "According to clinicopathologic characteristics, we identified that CRYAB, ECM1, GPX3, and CGNL1 may predict histological grade, UICC stage and lymph node metastasis." (PMID 32292720, 2020).
metastasis (2 papers, 2018 to 2022). The spread or migration of cancer cells from one part of the body (where they first appeared) to another. "Moreover, we have validated some previously reported overexpressed genes such as TGFB1, IBSP, MMP9, or ITGB3 in bone metastasis; CRYAB, NRCAM, and SOX2 in brain metastasis; VEGF and IL6 in lung metastasis; and CYP4F3 in liver metastasis." (PMID 34051058, 2022).
Obesity (2 papers, 2023 to 2025). Accumulation of substantial excess body fat. "Alpha B-crystallin (CRYAB), a member of the small heat shock protein family, is involved in apoptosis, inflammation, and redox regulation, and is associated with obesity and highly expressed in obese children." (PMID 41459085, 2025).
proteinopathies (2 papers, 2017 to 2019). "Future investigation is warrant to identify the specific E3 ligase responsible for CryAB ubiquitination/degradation, which would be crucial for understanding viral cardiomyopathy and other CryAB-related proteinopathies." (PMID 29088822, 2017). "This study reveals a novel function for CRYAB as a natural inhibitor of astrocytic autophagy and shows that knockdown of CYRAB may provide a therapeutic target against proteinopathies such as synucleinopathies." (PMID 30675347, 2019).
Senile plaques (2 papers, 2020 to 2025). Senile plaques are extracellular deposits of amyloid in the gray matter of the brain. "In our study, we evaluated p38 MAPK-dependent phosphorylation of CryaB (at serine position 59), which is a small chaperone protein associated with senile plaques and tau protein inclusions." (PMID 32731533, 2020). "As one of the criteria of p38 MAPKsp activity, we evaluated changes in the p38 MAPK-dependent phosphorylation level of a small chaperone protein (αB-crystallin, i.e., CryaB) associated with senile plaques and tau-protein inclusions." (PMID 32731533, 2020).
viral infection (2 papers, 2017 to 2025). "Following subsequent EBV and other viral infections, CRYAB, a heat shock protein (HSPB5), is expressed and presented to generate memory CRYAB-specific cells." (PMID 40327539, 2025). "We demonstrated that protein levels of CryAB were markedly decreased in the late stage of viral infection (i.e. 24 hours post-infection) in HL-1 mouse cardiomyocytes and rat neonatal cardiomyocytes." (PMID 29088822, 2017). "In addition, the combined beneficial effects of CryAB in defense against various types of cardiac injury and viral infection make it a very attractive drug target for clinical translation." (PMID 29088822, 2017). "We demonstrated that the expression of CryAB-WT conferred resistance to viral infection, as evidenced by reduced cytopathic effects, increased cell viability, decreased production of viral protein, significantly lowered viral titer (∼ 20 fold reduction) in CryAB-WT-overexpressing cells." (PMID 29088822, 2017). "Thus, it is postulated that impairing the integrity of the cytoskeletal network is an important strategy utilized by CVB3 to facilitate its propagation, and that overexpression of CryAB partially restores the functional network, resulting in reduced viral infection." (PMID 29088822, 2017). "Together, our results suggest that CryAB may act as an anti-viral protein against CVB3 and that dysregulation of CryAB may provide a favorable environment for effective viral infection." (PMID 29088822, 2017).
anaplastic astrocytoma (1 paper, 2019). "A study conducted on 18 grade III anaplastic astrocytomas has shown that the presence of the IDH1-R132H mutation was associated with the up-regulation of a truncated C-terminal form of Alpha-crystallin B chain protein (CRYAB)." (PMID 31357616, 2019).
cervical squamous cell carcinoma (1 paper, 2022). A squamous cell carcinoma arising from the cervical epithelium. "CRYAB gene was significantly upregulated in the advanced pathological stage of COAD, cervical squamous cell carcinoma and endocervical adenocarcinoma (CESC), STAD, ovarian serous cystadenocarcinoma (OV), and BLCA (P < 0.05)." (PMID 36713654, 2022).
chronic hepatitis B (1 paper, 2025). "In chronic hepatitis B (CHB) patients, immune active phase (IA) is associated with higher intrahepatic expression of MSX1, DNAJA4 and CRYAB, and lower serum HBV markers compared to immune tolerant (IT) phase." (PMID 39883729, 2025).
cocaine addiction (1 paper, 2025). "Therefore, EAAT2, which may be associated with the modulatory role of CRYAB in cocaine addiction, was selected as the target protein." (PMID 40095747, 2025).
colon adenocarcinoma (1 paper, 2021). "In well-differentiated colon adenocarcinoma (G1), CRYAB protein was present in the muscolaris mucosae, in the neural structures, in the interstitial cells of Cajal, and in the intramural nerve plexuses, while it was absent in the neoplastic glandular structures." (PMID 34069924, 2021).
congenital cataracts (1 paper, 2015). "Here, we report two novel mutations in CRYAB associated with autosomal recessive congenital cataracts identified in consanguineous Pakistani families." (PMID 26402864, 2015).
enterovirus infection (1 paper, 2025). "Conversely, during enterovirus infection, the degradation and phosphorylation of CRYAB promote viral replication and contribute to viral pathogenesis." (PMID 40688463, 2025).
epilepsy (1 paper, 2024). A brain disorder characterized by episodes of abnormally increased neuronal discharge resulting in transient episodes of sensory or motor neurological dysfunction, or psychic dysfunction. "Considering the association between repeated kindled seizures and increased seizure susceptibility along with reduced seizure thresholds, the upregulation of CRYAB may indicate its involvement in the pathophysiological mechanisms underlying epilepsy development." (PMID 38971757, 2024). "Regarding epilepsy, elevated levels of immunoreactive CRYAB in astrocytes and oligodendrocytes have been identified in pediatric epileptic patients." (PMID 38971757, 2024). "The decreased plasma CRYAB in epilepsy is of particular interest, as early studies describe an increase in the expression of CRYAB in astrocytes and oligodendrocytes of the neocortex, hippocampus, and amygdala in pediatric epilepsy patients." (PMID 38971757, 2024). "Notably, low plasma levels of heat shock 70 protein, a family member of CRYAB, were also found after an acute stroke to be predictive of epilepsy in a large-scale study." (PMID 38971757, 2024).
familial cardiomyopathy (1 paper, 2012). An instance of cardiomyopathy that is caused by an inherited modification of the individual's genome. "In another example of myocardial protein dysregulation, a R120G mutation in CryAB (crystallin, alpha B), a small heat shock protein, is linked to familial cardiomyopathy." (PMID 22536506, 2012).
ischemic cardiomyopathy (1 paper, 2025). Ischemic cardiomyopathy is a cardiomyopathy in which a weakness in the muscle of the heart due to inadequate oxygen delivery to the myocardium with coronary artery disease being the most common cause. "Thus, targeting CRYAB phosphorylation-induced condensatopathy is an attractive strategy to counter ischemic cardiomyopathy." (PMID 39932799, 2025).
lateral sclerosis (1 paper, 2012). Primary lateral sclerosis (PLS) is an idiopathic non-familial motor neuron disease characterized by slowly progressive upper motor neuron dysfunction leading to spasticity, mild weakness in voluntary muscle movement, hyperreflexia, and loss of motor speech production. "Expression of SLC24A5, MMP115, and TYR, and genes for crystalline alphaB (CRYAB), Shikimate 5-dehydrogenase and amyotrophic lateral sclerosis 2 (ALS2) were commonly depressed in AV and CV samples relative to BL controls." (PMID 22500953, 2012).
MELAS (1 paper, 2022). "On the contrary, the expression of HSPB1, CRYAB and S100A9 were significantly up-regulated in MELAS patients." (PMID 36254078, 2022).